NACC2 (NACC family member 2)
Description:
Functions as a transcriptional repressor through its association with the NuRD complex.
Synonyms: NAC-2; BTBD14A; RBB; MGC23427; BEND9; BTBD31; BTBD14
Tractability: PROTAC: UniProt records ubiquitination sites on it; ubiquitination databases record sites on it.
Gene: Protein-coding gene on chromosome 9 (136,006,537 to 136,095,289, reverse strand). Ensembl gene ENSG00000148411.
Subcellular location: Nucleus
Subcellular location (Human Protein Atlas): Mitochondria; Nucleoli
Gene Ontology:
Molecular function: DNA-binding transcription repressor activity, RNA polymerase II-specific; histone deacetylase binding; protein binding; protein homodimerization activity; protein-containing complex binding; RNA polymerase II cis-regulatory region sequence-specific DNA binding; DNA-binding transcription factor activity, RNA polymerase II-specific; DNA binding
Biological process: negative regulation of cell population proliferation; negative regulation of DNA-templated transcription; negative regulation of transcription by RNA polymerase II; positive regulation of intrinsic apoptotic signaling pathway in response to DNA damage; protein homooligomerization; protein-containing complex localization; regulation of transcription by RNA polymerase II; regulation of cell population proliferation
Cellular component: chromatin; nucleus
Genetic constraint (gnomAD): Loss-of-function variants: 4 observed, 16.05 expected, observed/expected ratio (o/e) 0.25, 90% interval 0.12 to 0.57. The upper end of that interval is the gene's LOEUF score, 0.57, which puts it in group 2 of 6, group 1 being the genes least tolerant of losing a copy. Missense variants: 198 observed, 285.42 expected, observed/expected ratio (o/e) 0.69, 90% interval 0.62 to 0.78. Synonymous variants: 144 observed, 120.54 expected, observed/expected ratio (o/e) 1.19, 90% interval 1.04 to 1.37.
Homologues: Orthologues: chimpanzee NACC2 (99% identical), macaque NACC2 (99% identical), dog NACC2 (94% identical), pig NACC2 (93% identical), guinea pig NACC2 (93% identical), mouse Nacc2 (93% identical), rat Nacc2 (92% identical), tropical clawed frog nacc2 (78% identical). Paralogues in human: NACC1 (48% identical), ZBTB21 (19% identical), ZBTB33 (15% identical), BCL6 (15% identical), ZBTB46 (15% identical), ZBTB14 (13% identical), ZBTB12 (12% identical), ZBTB49 (12% identical), BCL6B (12% identical), ZBTB7B (12% identical), ZBTB26 (11% identical), ZBTB25 (11% identical), and 16 more.
Diseases named in the same sentence as NACC2 in open-access papers:
NACC2 is named in the same sentence as 9 diseases in open-access papers, as found by Europe PMC text mining. Sharing a sentence is not in itself a finding about the gene and the disease. The quoted sentences say what the papers report.
glioma (2 papers, 2020 to 2021). A benign or malignant brain and spinal cord tumor that arises from glial cells (astrocytes, oligodendrocytes, ependymal cells). "Two reports describe patients suffering from a low-grade glioma (LGG), one with a NACC2:NTRK fusion showing more than 50% reduction in tumor volume and an ETV6:NTRK3-fused tumor with complete remission upon treatment with larotrectinib." (PMID 33353026, 2020).
pilocytic astrocytoma (2 papers, 2022 to 2026). Pilocytic astrocytoma is a rare subtype of low-grade glioma of the central nervous system characterized by a well circumscribed, often cystic, brain tumor with a discrete mural nodule and long, hair-like projections that extend from the neoplastic astrocytes. "NACC2 has also been identified as an NTRK fusion protein, specifically in pilocytic astrocytoma." (PMID 37066112, 2022).
glioblastoma (1 paper, 2025). The most malignant astrocytic tumor (WHO grade IV). "One glioblastoma patient with a NACC2::NTRK2 fusion was still in remission two years after treatment with conventional therapy." (PMID 41331048, 2025).
prostate carcinoma (1 paper, 2022). A carcinoma that arises from epithelial cells of the prostate gland. "Of all the genes, NACC2 gene alterations were reported in 105/4990 (2.1%) prostate cancer samples." (PMID 36468011, 2022). "In comparison, there were no obvious associations between the expression levels of ABHD2, FGF2, DCAF7, GSK3B, NACC2, DICER1, and FGFR1OP genes and survival rate in prostate cancer patients." (PMID 36468011, 2022).
cancer (3 papers, 2021 to 2024). A tumor composed of atypical neoplastic, often pleomorphic cells that invade other tissues. "Our results showed that majority hub genes DCAF7, FGF2, GSK3B, NACC2, and NFIB were highly expressed and (nTPM >19) localised mainly in the nuclei of the cancer cells." (PMID 36468011, 2022).
tumor (3 papers, 2014 to 2025). "NACC2 encodes a protein that acts by protein-protein association functioning as a transcriptional regulator, controlling the expression of genes involved in neural development and differentiation, and in developmental signals, potentially as a tumor suppression." (PMID 40575267, 2025).
NACC2 also shares sentences with these, for which no sentence is quoted: infection (1 paper); leukaemias (1); prostate adenocarcinoma (1).